ENSG00000274547
Gene: Miscellaneous RNA gene on chromosome 2 (44,938,833 to 44,939,028, forward strand). Ensembl gene ENSG00000274547.
Gene Ontology:
Biological process: regulation of gene expression